CD47 (CD47 molecule)
Diseases named in the same sentence as CD47 in open-access papers (continued):
Sharing a sentence is not in itself a finding about the gene and the disease.
tumor (continued). "Moreover, our findings suggest MφNP can potentially restore the phagocytic activity of standard macrophages by obstructing the CD47-SIRPα interaction within the TAM in the tumor microenvironment." (PMID 38111068, 2023). "Briefly, the CD47 cell surface receptor on tumor cells forms a complex with signal-regulatory protein alpha (SIRPα) on phagocytic cells, resulting in the recruitment of SHP-1 and SHP-2 that prevent the accumulation of myosin IIA in the phagocytic synapse, ultimately inhibiting phagocytosis." (PMID 37373873, 2023). "Disrupting either MHC-I or LILRB1 can facilitate phagocytosis, suggesting that the MHC-I/LILRB1 axis plays a vital role in inhibiting macrophage phagocytosis, which shows potential to be a possible marker for therapeutic response to CD47-targeted agents and target of anti-tumor therapy." (PMID 37345054, 2023). "CD47 antibody promoted the phagocytosis of both control and knockdown tumor cells by macrophages." (PMID 36823443, 2023). "The binding of CD47 to SIRPα expressed on macrophages prevents the phagocytosis of tumor cells." (PMID 37108657, 2023). "Monotherapy by CD47 blockade leads to a reduction in tumor growth and an increase in OS." (PMID 36794651, 2023). "Our findings suggest that a combination of CD47 blockade and desialylation may be necessary to optimize cancer immunotherapy, considering the upregulation of checkpoint molecules by tumor cells to evade immune surveillance." (PMID 37444515, 2023). "Here, a microfluidics‐enabled nanovesicle using ultra‐pH‐sensitive polymer mannose‐poly(carboxybetaine methacrylate)‐poly(hydroxyethyl piperidine methacrylate) (Man‐PCB‐PHEP) is developed to deliver CD47/PD‐L1 antibodies (NCPA) for tumor‐acidity‐activated immunotherapy." (PMID 37132609, 2023). "Given that CD47 is overexpressed in a variety of tumor cells, ICD plus aCD47 may be a potential strategy for overcoming ICD inducer resistance in cancer immunotherapy." (PMID 37144580, 2023). "Recent research has shown that the CD47/SIRPα axis controls the destiny of tumor cells." (PMID 36726125, 2023). "Importantly, Cd47 knockdown also substantially increased the infiltration of M1 macrophages in tumor tissues and the phagocytosis of tumor cells by M1 macrophages in vivo." (PMID 36413402, 2023). "HX009 binds to PD-1 expressed on T cells and CD47 on tumor cells." (PMID 36900399, 2023). "Furthermore, a therapeutic blockade of CD47 by antibodies or suppression of CD47 expression is sufficient to enhance the direct TCR-dependent killing of tumor cells by mouse or human CD8 T cells." (PMID 36768931, 2023). "Tumor growth inhibition in xenograft models suggests that innate immunity alone contributes to the efficacy of CD47-targeted therapy, but could also indicate that immune-independent mechanisms are involved." (PMID 37958404, 2023). "Hence, tumor cells express CD47 protein that is then able to bind with SIRPα receptor on myeloid cells such as macrophages and neutrophils." (PMID 36109471, 2023). "HuNb1-IgG4 nanobody exhibited superior anti-tumor efficacy compared to the clinical anti-CD47 mAbs." (PMID 36761751, 2023). "These immune infiltrates likely create an anti-inflammatory microenvironment, which is in line with the fact that M2 macrophages outnumber M1 macrophages in nearly all types of sarcomas and that these tumor cells express CD47, which downregulates proinflammatory macrophage activity." (PMID 36768342, 2023). "Previous studies have shown that targeting the CD47/SIRPα axis with anti-CD47 agents (including antibodies and SIRPα-Fc fusion proteins) promotes the phagocytosis of tumor cells by macrophages in vitro, and inhibits tumor growth in many human tumor xenograft models." (PMID 36650558, 2023).
tumor (continued). "High CD47 tumor cell expression or high counts of CD68 macrophages were significantly associated with elevated levels of all TIL subsets (p < 0.02), CD163 macrophages (p < 0.001), blood vessel invasion (CD31 positive) (p < 0.01), and high tumor cell Ki67 (p < 0.004)." (PMID 36598153, 2023). "CD47 acts as a checkpoint that provides a "don't-eat-me" signal to macrophages via interaction with its surface protein SIRPα, resulting in immune evasion by the tumor cells." (PMID 37626420, 2023). "CD47 is expressed in normal and cancer cells and sends “don’t eat me” signals to macrophages, which is an important way for normal cells to protect themselves from phagocytosis and a pathway for immune escape of tumor cells." (PMID 37810971, 2023). "PD-L1/PD-1- and CD47/SIRPα-targeting ΙO could eventually unleash the anti-tumor potential of activated lymphocytes and monocytes." (PMID 37232754, 2023). "Aside from tumor cell-target therapeutics like anti-CD47 antibodies and PD-1 blockade, other macrophage-related checkpoints are also identified, such as CD40 agonists, B7-H4 (aka B7x, B7S1 or VTCN1) and V-domain Ig- containing suppressor of T cell activation (VISTA, aka PD-1H, DD1α)." (PMID 37426676, 2023). "Moreover, the CD47-SIRP pathway has a major impact on these macrophages’ phagocytic activity against tumor cells that express CD47 since these macrophages express SIRP on their surface." (PMID 36903458, 2023). "Thus, attributing the effects of CD47 blockade solely to the inhibition of the phagocytosis checkpoint is an oversimplification, as its efficacy is likely determined by the net effect of pro- and anti-tumor mechanisms regulated by CD47." (PMID 37958404, 2023). "Then, the tumor-bearing mice were subjected to anti-CD47, cordycepin, and combination treatments." (PMID 37138855, 2023). "For example, CD47 blockage on CD8+T cells mediates immunogenic tumor destruction." (PMID 37275901, 2023). "Finally, in a heterotopic xenograft model, the administration of anti-CD47 antibodies inhibited tumor growth." (PMID 36860925, 2023). "PD-L1 and CD47 are both highly expressed in tumor cells and can be simultaneously regulated by MYC." (PMID 37546397, 2023). "Blocking CD47/SIRPα signaling enhances the anti-tumor effect of CAR-T cells." (PMID 38136311, 2023). "Interestingly, Cd47 is a “don’t eat me” signal, which indicates that tumor cells would avoid being phagocytosed by immune cells." (PMID 37095087, 2023). "Both studies showed reduced tumour growth with anti-CD47 treatment." (PMID 36900335, 2023). "However, the immune system can be circumvented by tumor cells in a variety of ways, one of which is by upregulating integrin-associated protein (IAP-) CD47." (PMID 37719086, 2023). "High expression of CD47 contributes to tumor cell proliferation and tumor metastasis." (PMID 36882399, 2023). "Antibody-mediated CD47 blockade also enhanced phagocytosis by macrophages and dendritic cells and inhibited tumor growth in A549 and H1975 xenograft as well as LLC syngeneic tumor models, which was associated with an increase in intratumoral macrophages." (PMID 37958404, 2023). "gETL NPs were fused by thermosensitive liposome and CD47-expressing EVs, which could efficiently deliver granulocyte–macrophage colony-stimulating factor and docetaxel to tumor and release them under hyperthermic intraperitoneal chemotherapy (HIPEC)." (PMID 37717008, 2023). "The function of EpCAM-AsiCs in the process of cancer immunity was evaluated in genetically engineered mouse breast cancer models, which indicated that Upf2, Parp1, Cd47, and Mcl1 knockdown by EpCAM-AsiCs obviously inhibited tumor progression and promoted tumor-infiltrating immune cell functions." (PMID 36969696, 2023). "Bispecific antibodies are also likely to enhance the tumor selectivity of CD47 blockade." (PMID 37958404, 2023).
tumor (continued). "The tumor accumulation of Cy7‐labeled antibody in anti‐CD47‐PCM@NP was over two times greater than the anti‐CD47 group on the observed time points, confirmed by fluorescent imaging of tissue (tumor, heart, lung, liver, spleen, and kidney) slices and tissue distribution analysis." (PMID 36683161, 2023). "In addition, multiplex fluorescent immunohistochemistry (mIHC) staining shows that PD-L1 and CD47 co-express on several different types of human tumor tissues." (PMID 36593962, 2023). "Even though the anti-CD47 arm is low affinity, this arm could induce the macrophage phagocytosis of tumor cells both in vitro and in vivo." (PMID 36593962, 2023). "For CD47 and PD-L1 double positive patients, 6MW3211 may preferentially bind to tumor cells followed by the activation of both innate and adaptive immunity." (PMID 36593962, 2023). "Importantly, immunohistochemical staining of control normal lymph nodes and NHL tumor samples showed a relatively high proportion of CD47+ cells in the latter group." (PMID 37781520, 2023). "In addition, CD24, similar to CD47 and PD-L1 checkpoints, can reverse the function of immune cells, resulting in overall pro-tumour progression." (PMID 38137380, 2023). "The tumor micro-environment features a marked expression of SIRPα, an inhibitory receptor present on myeloid cells, as well as its widely distributed counter-receptor CD47." (PMID 38283146, 2023). "Furthermore, CD47 is also an important marker for M2-type TAMs, and anti-CD47 therapy can reprogram TAMs to proinflammatory (M1-type) macrophages to kill tumor cells and prevent tumor metastases in human solid tumors." (PMID 36845095, 2023). "Anti-CD47 therapy resistance of tumor cells may be restored by treatment with an LILRB1-blocking antibody." (PMID 38033495, 2023). "Moreover, CD47 antagonists destroy tumor cells utilizing natural killer cell-mediated antibody-dependent cytotoxicity (ADCC) and complement-dependent cytotoxicity (CDC)." (PMID 36726125, 2023). "Strategies for antagonizing CD47 in cancer models have primarily involved the use of anti-CD47 mAbs delivered via intraperitoneal injection, intratumoral injection, or ex vivo coating of tumor cells prior to implantation into mice." (PMID 37958404, 2023). "Recently, a fusion protein of CBD and the Fc of SIRPα (signal regulatory protein α), which targets the SIRPα-CD47 axis, showed accumulation in the tumor tissue, more antitumor activity and an increase infiltration of M1-like macrophages than SIRPα Fc alone, in a xenograft model of NSCLC." (PMID 37284199, 2023). "Combining the HER2 CAR with GD2 CAR, CD276 CAR in combination with anti-CD47 antibody therapy may prove to be sufficiently potent to eradicate DIPG tumor cells in the brain and warrants further investigation." (PMID 37152812, 2023). "Calreticulin’s action on tumor-invaded bone and its interaction with CD47." (PMID 36943734, 2023). "In addition, we compared significant immune checkpoints between “stiff tumor” and “soft tumor” and observed the expression of CTLA4, CD276 and TNFRSF25 was higher in “stiff tumor”, while the expression of CD47 was higher in “soft tumor”." (PMID 37179366, 2023). "Likewise, CD47 is overexpressed on many tumor cells (in relation to normal cells), allowing tumor cells to escape immune surveillance through inhibition of phagocytosis." (PMID 36459066, 2023). "SIRPα binds with CD47 to initiate a signaling cascade which results in the inhibition of phagocytosis, a critical “do not eat me” signal for the innate immune system which is overexpressed on many kinds of tumor cells." (PMID 36827121, 2023). "Despite the promising preliminary results observed in the various clinical trials targeting the CD47-SIRPα axis, it is important to consider the ways by which tumor cells may adopt resistance against these therapies." (PMID 35884427, 2022).
tumor (continued). "Hence, the combination of the nanoplatform with CD47 blockade suppressed tumor growth and distant metastasis and prevented tumor recurrence by triggering a long-term antitumor immunity." (PMID 35335881, 2022). "CD47 also affects TAMs polarization, and the anti-CD47 antibody increased the ability of macrophages to phagocytose tumor cells by blocking the interaction of CD47 with SIRPα on macrophages, which has been demonstrated in various preclinical models of solid tumors." (PMID 36225938, 2022). "Although the CD47 monoclonal antibody (aCD47) strategy has been extensively studied in clinical trials, the depletion of aCD47 by red blood cells (RBCs) and the resulting hematotoxicity have impeded their application in tumor treatment." (PMID 35832081, 2022). "For instance, galectin-1, galectin-3, and CD47 are expressed on the tumor cell membrane." (PMID 36382024, 2022). "The c-MYC gene leads to increased expression of PD-L1 and CD47 at the surface of tumor cells." (PMID 37305016, 2022). "In CTCL, CD47 is overexpressed in advanced MF and SS patients where it works in tandem with thrombospondin-1 to, not only allow for immune evasion, but also promote tumor cell migration and survival." (PMID 36059451, 2022). "Therefore, a series of clinical studies targeting CD47 protein are expected to bring new hope to the field of tumor therapy." (PMID 36212414, 2022). "The LN-derived tumor cells expressed higher levels of costimulatory and adhesion molecules as well as molecules associated with B-cell activation, including Ki67, PD-1, CD200, and CD47." (PMID 36922932, 2022). "Indeed, tumors treated by anti-CD47 antibody showed an increased antibody binding to tumor cells, whereas tumor binding antibody was less intensified in tumors treated with ET, indicating again that blocking FAO reduces CD47 expression." (PMID 35314680, 2022). "Similarly, to escape immune system tumor cells express on their surface CD47 that functions as an inhibitor of phagocytosis following its interaction with the signal-regulatory protein alpha (SIRPα) expressed on macrophages cell surface." (PMID 35493456, 2022). "The FAO-mediated CD47 expression may contribute to the overall tumor adaptive (acquired) resistance with the feature of aggressive growth and anti-phagocytosis." (PMID 35314680, 2022). "Furthermore, the function of the CD47/SIRPα axis was established in the late 2000s and has been termed the first tumor phagocytosis-related checkpoint (also known as the macrophage “don’t eat me” signal)." (PMID 35317832, 2022). "Antibodies targeted to CD47 could induce direct killing of tumor cells by inhibiting protein kinase A via Giα, resulting in clustering of CD47 in the membrane, and caspase-independent programmed cell death." (PMID 35418166, 2022). "Only the IgA treated mice showed reduced tumor size for the CD47 KO tumor." (PMID 35865547, 2022). "Notably, despite the excellent clinical performance shown by CD47/SIRPα antibodies, the limitations of antibody drugs, including poor tumor permeability, undesirable oral bioavailability and poor stability, hinder their clinical application." (PMID 36080360, 2022). "Similarly, the expression of CD47 protein on the surface of tumor cells is also affected by HIF-1α, and hinder the phagocytic ability of phagocytes to tumor cells through phosphorylation of signal regulatory proteins on the surface of macrophages α (SIRP α)." (PMID 36212414, 2022). "CD47 is a well-documented “don’t eat me” signal which interacts with the signal regulatory protein alpha (SIRPα) on the surface of macrophages, therefore protecting tumor cells against macrophagic phagocytosis." (PMID 36080223, 2022). "Cell–cell contacts between neutrophils and CD47-expressing or CD47-deficient SKBR3 cells were analyzed and indicated that disruption of the CD47-SIRPα axis resulted in the promotion of neutrophil–tumor cell interactions in the presence of tumor-targeting antibodies." (PMID 35884427, 2022).
tumor (continued). "The lower therapeutic effect of anti-CD47 mAbs may result from antibody sequestration by the healthy tissue “sink”, which thereby limits the blockade efficiency against the tumor cells." (PMID 36439116, 2022). "Given the popular application of CD47-SIRPα blockade in tumor immunotherapy, its impact on T cell generation/regeneration and therapeutic efficacy might be of particular interest." (PMID 35511221, 2022). "Notably, tumor cells often overexpress CD47 on their cell membrane to evade immune-mediated tumor cell killing." (PMID 35884427, 2022). "We found that extracellular vesicles (EVs), including exosomes (Exos) from cells transgenically overexpressing CD47 or tumor cells overexpressing endogenous CD47, could induce CD47 cross-dressing on pig or human cells." (PMID 36454036, 2022). "On the surface of tumour cells, CD47 binds TSP during the whole lifespan, creating a distinct binding profile that may enable ‘untargeting’ of young RBCs." (PMID 35908284, 2022). "c-Myc depletion greatly reduced basal and doxorubicin-induced CD47 expression in tumor tissues." (PMID 36274066, 2022). "Co-enhancement of FAO enzymes with CD47 was then accessed by in vivo U251 tumor model." (PMID 35314680, 2022). "Interfering with the CD47-SIRPα interaction slowed tumor growth and prevented metastasis." (PMID 35865547, 2022). "It is known that CD47 is overexpressed on the surface of most tumors and interacts with signal regulatory protein α (SIRPα) on phagocytes, which greatly limits the ability of macrophages to phagocytize tumor cells." (PMID 34973131, 2022). "CD47 is expressed at a high level on the cell surface by a variety of malignant cells; notably, its blockade with monoclonal antibodies allows the efficient phagocytosis of cancer cells and leads to tumor rejection and the development of antitumor immunity." (PMID 35565443, 2022). "Notably, CXCR4/CXCL12 cross-signal via the T and B cell receptors (TCR and BCR) and co-internalize with CD47, promoting tumor cell phagocytosis by macrophages in an anti-tumor immune process called ImmunoGenic Surrender (IGS)." (PMID 35565443, 2022). "CD47 (a transmembrane protein) is highly expressed in tumor-derived exosomes." (PMID 35078498, 2022). "Furthermore, SHP1 is a key inhibitor of SIRPα (on macrophage)-CD47 (on tumor) for “don’t eat me” signaling." (PMID 36686648, 2022). "CD47 inhibition has also been shown to prime CD8 effector T cells with tumour specificity by increasing antigen processing and presentation by dendritic cells and tumour-associated macrophages in pre-clinical studies." (PMID 35954487, 2022). "Meanwhile, the released anti‐CD47 antibody could elicit enhanced tumor‐phagocytosis of macrophages via blocking the CD47‐SIRPα checkpoint." (PMID 37323705, 2022). "Accordingly, treatment with CD47 blockade could inhibit tumor growth via macrophage-mediated mechanism." (PMID 36454036, 2022). "Blocking FAO impairs tumor growth and reduces CD47 anti-phagocytosis." (PMID 35314680, 2022). "This indicates that the CD47-SIRPα interaction is a key suppressor in the tumor microenvironment." (PMID 35865547, 2022). "The strategy targeting CD47 on tumor cells has been the most commonly studied." (PMID 35557862, 2022). "Thus, although CD47-SIRPα appears to enhance tumor killing, the therapy is dependent on the opsonization of the tumor cells and possibly also the immunosuppressive state of the TME." (PMID 35884427, 2022). "Disrupting the interaction between CD47 and SIRPα may therefore promote anti-tumor effects by neutrophils and macrophages." (PMID 35884427, 2022). "Thus, even though CD47-SIRPα disruption and tumor-opsonizing IgG are separately ineffective against established metastatic solid tumors, their combination in molecular and cellular therapies prolongs survival." (PMID 35454837, 2022). "Also, when looking closer to the peripheral compartment of the SGC TME, we found significantly higher proportions of CD47+ TIIC compared to CD47+ tumor cells." (PMID 36171566, 2022).